HIF1A (hypoxia inducible factor 1 subunit alpha)
Diseases named in the same sentence as HIF1A in open-access papers (continued):
Sharing a sentence is not in itself a finding about the gene and the disease.
lymphoma (continued). "Our findings showed that hypoxic culture upregulated the expression of HIF-1α and its target genes in canine lymphoma cells, and enhanced their growth rate, DOX resistance, and invasiveness." (PMID 28489881, 2017). "(2013) found that genetic deletion of AMPK α1 accelerates Myc‐driven lymphoma due to elevations in mTORC1 activity and subsequent increases in HIF1α that promoted aerobic glycolysis (Warburg effect)." (PMID 28544264, 2017). "While HDACI are being combined with multiple anticancer agents, only a few promising strategies targeting HIF-1α in lymphoma are currently under development." (PMID 24312289, 2013). "Lymphoproliferative diseases and lymphoma were found in 81% and 44% of HIF1A TG homozygous mice, 81% and 38% of the heterozygotes, and 17% and 8% of wild-type mice, respectively (p<0.01 for heterozygotes vs. WT on lymphoproliferative diseases)." (PMID 23593116, 2013). "We next examined the phenotype and proliferative capacity of lymphocytes from the HIF1A TG mice, since lymphoproliferative diseases and lymphomas were frequently observed in the mice." (PMID 23593116, 2013). "All the cell lines showed significant expression of HIF-1α protein under normoxia, while no HIF-1α protein was observed in normal lymphocytes, suggesting that HIF-1α is constitutively active in lymphoma cell lines under normoxia." (PMID 24312289, 2013). "The lymphoma cells detected in our HIF1A TG mice showed T cell phenotype determined by FCM and clonal rearrangement of T cell receptors concomitant with an increase of angiogenesis in tumor tissues." (PMID 23593116, 2013). "Furthermore, MJ can relieve the chemoresistance role of HIF-1α on lymphoma cells in in vitro experiments." (PMID 37588219, 2024). "HIF-1α plays an important role in the pathogenesis of lymphoma." (PMID 36982568, 2023). "We found that PMA led to increased HIF-1α accumulation in EL4 lymphoma cells and EL4 tumors, indicating that it may have a role in PD-1 expression." (PMID 35250391, 2022). "MYC also has been shown to cross-talk with HIF1α in this lymphoma." (PMID 36428647, 2022). "Interestingly, increased expression of GAPDH mRNA in biopsies from DLBCL patients correlated with higher levels of HIF1α and NFκB, and this axis was shown to promote lymphoma vascularization and aggressiveness." (PMID 36428647, 2022). "To determine whether the overexpression of HIF-1α counteracts the effect of miR-346 in lymphoma cells, we co-transfected miR-346 mimic or mimic control with or without HIF-1α overexpression vector into Raji cells." (PMID 32403237, 2020). "As such, targeting the hypoxic microenvironment through modulation of HIF1α could be an effective target in limiting BM involvement in lymphoma growth." (PMID 32019190, 2020). "This evidence reinforces the novel hypothesis that HIF-1α plays a major role in the chemoresistance mechanism or promotes the activation of drug transporters in lymphoma cells." (PMID 28489881, 2017). "We tested the hypotheses that hypoxic stimulation enhances growth potentials of canine lymphoma cells by activating hypoxia-inducible factor 1α (HIF-1α), and that the hypoxia-activated prodrug (TH-302) inhibits growth potentials in the cells." (PMID 28489881, 2017). "Yet, despite reduced tumour burden in HIF-1α KO mice, the number of tumour infiltrating NK cells and as well as the expression of the cytotoxic effector molecule Granzyme B in NK cells was lower than in lymphomas from WT littermates." (PMID 29150606, 2017). "Indeed, we identified an HIF-1α inhibitor, chetomin, as a promising anti-lymphoma drug candidate with an IC50 of 1.3 nM." (PMID 28055963, 2017). "HIF-1α protein was constitutively increased in lymphoma cells without PCI-24781 treatment, but the HDACI caused a further increase in HIF-1α protein, compared with untreated cells during the 0-6 hr period." (PMID 24312289, 2013). "Notably, radiotherapy of lymphoma exhibited enhanced NF-κB activation and high level of HIF-1α." (PMID 36599894, 2023).
lymphoma (continued). "Inhibition of HIF-1α may have a therapeutic effect on lymphoma." (PMID 36982568, 2023). "Importantly, HIF1α has also been found to be upregulated in lymphomas, especially in DLBCL." (PMID 32019190, 2020). "Thus we measured expression of HIF-1α protein in Myr-Akt transfected lymphoma cells." (PMID 24312289, 2013). "We next investigated the factors that might regulate HIF-1α in lymphoma cells under normoxia." (PMID 24312289, 2013). "Recent studies reported that in mouse lymphoma model and human acute myeloid leukemia (AML) stem cells aberrant activation of HIF-1α was observed, which led to the stimulation of its signaling cascade even under normoxic conditions." (PMID 35870078, 2022). "For example, 17-AAG, an Hsp90 inhibitor, induced apoptosis and disrupted transcriptional functionality of HIF1α, which is a client protein of Hsp90, and 17-AAG decreased the colony formation ability of mouse lymphoma CSCs and human myeloid leukemia CSCs." (PMID 33390934, 2020). "Therefore, determining the relationship between HIF-1α activation and the survival potential of canine lymphoma cells under hypoxic conditions may provide insight into tumorigenesis and provide medically valuable information for the treatment of both NHL and canine lymphoma." (PMID 28489881, 2017). "Our rationale to target HIF-1α and autophagy via a combination of HDACI and autophagy inhibitors represents a novel therapeutic option for the treatment of lymphoma." (PMID 24312289, 2013). "Intratumoral gene transfer of an antisense HIF-1α plasmid has been shown to downregulate VEGF and decrease tumor microvessel density in an EL-4 mouse lymphoma model, resulting in the complete and permanent NK cell rejection of small tumors (0.1 cm in diameter)." (PMID 36980629, 2023). "Moreover, the conditional deletion of HIF-1α in NK cells decreased tumor burden and enhanced survival in several cancer models, including RMA-S lymphoma, Lewis lung carcinoma and B16-Rae1 melanoma." (PMID 36980629, 2023). "Agents targeting HIF-1α signaling such as EZN-2968 (HIF-1α antisense mRNA) and PX-478 (small molecule inhibitor of HIF-1α) have been effective treatments for advanced solid tumors and lymphoma in phase I clinical trials." (PMID 30618749, 2018). "In that study, atorvastatin was found to induce the miR-346-mediated inhibition of HIF-1α in Raji cells, followed by the suppression of VEGF expression and VEGF-stimulated angiogenesis, which elevated the efficacy of radioimmunotherapy toward the lymphoma xenografts growing in mice." (PMID 33806538, 2021). "The high expression of HIF-1α and its further increase in response to PCI-24781 at early time points to the extent that HIF-1 promotes growth and survival in DLBCL cells may promote lymphoma progression." (PMID 24312289, 2013). "Immunohistochemistry (IHC) techniques were used to examine the protein expression of HIF‐1α in paraffin‐embedded myeloid tissues from 82 patients with MDS and 33 controls (patients with lymphoma that is not invading myeloid tissues)." (PMID 31411003, 2019).
diabetic retinopathy (45 papers, 2014 to 2026). "Muller cells have possibilities to play an important role in the production of VEGF and HIF-1α, which are associated with inflammation of the inner retinal layers, such as in diabetic retinopathy." (PMID 38187496, 2023). "Diabetic retinopathy had one disease-associated gene that was differentially expressed during spaceflight (Hif1a)." (PMID 31527661, 2019). "In addition, HIF1α-linked angiogenesis was also recognized as an important mechanism for the molecular pathogenesis of diabetic retinopathy." (PMID 39457541, 2024). "Indeed, such an HIF1α linked stimulation of the angiogenesis was also recognized as a pivotal mechanism that is associated with the molecular pathogenesis of diabetic retinopathy." (PMID 35628282, 2022). "Hypoxia-driven overexpression of vascular endothelial growth factor (VEGF) and hypoxia-inducible factor-1α (HIF-1α) is central to diabetic retinopathy (DR) pathogenesis." (PMID 41169477, 2025). "In diabetic mice SIRT1 exerts an antiangiogenic role in diabetic retinopathy via microRNA (miR)-20a elevation and yes-associated protein/HIF-1α/vascular endothelial growth factor A (YAP/HIF-1α/VEGFA) downregulation." (PMID 41011644, 2025). "In diabetic retinopathy (DR), hypoxia-inducible factor (HIF-1α) induces oxidative stress by upregulating glycolysis." (PMID 38448948, 2024). "When diabetic retinopathy develops, the microenvironment in the retina experiences hypoxia, which triggers an increase in the expression of HIF1α." (PMID 37828620, 2023). "Literature was reviewed from common science libraries PubMed and Embase using various combinations of the search terms “diabetic retinopathy,” “HIF-1a,” “caspase-1,” and “IL-1B”." (PMID 37637673, 2023). "Increased HIF-1α level played a protective role in the diabetic heart and kidney but aggravated diabetes retinopathy." (PMID 36017378, 2022). "Hif-1α is a key mediator and target of retinal neovascularization and diabetic retinopathy, and during hypoxia, Sirtuin 1 (Sirt1) is downregulated, which allows the acetylation and activation of Hif-1α." (PMID 35346383, 2022). "HIF-1α and VEGF induced by HIF-1α are closely related to the development and progression of diabetic retinopathy and age-related macular degeneration (AMD)." (PMID 33923349, 2021). "VEGF increases vascular permeability and promotes pathological neovascularization in various ocular diseases, such as age-related macular degeneration and diabetic retinopathy, and its expression is also regulated by HIF-1α during hypoxic conditions." (PMID 31546635, 2019). "The aim of this study was to determine the retinal content of vascular endothelial growth factor (VEGF) and hypoxia-inducible factor-1α (HIF-1α) in experimental diabetic retinopathy and to assess the effect of pharmacological blockade of cellular protein kinases with sorafenib on these parameters." (PMID 41169477, 2025). "This state may lead to relatively decreased oxygen levels in the surrounding tissue, which can be speculated to have similar mechanisms to VHL expression and HIF-1α in diabetic retinopathy." (PMID 38732107, 2024). "It was reported that formononetin (7-hydroxy-4′-methoxyisoflavone) had potential to treat diabetic retinopathy by inhibiting the secretion of vascular endothelial growth factor (VEGF) in the HIF-1α/VEGF signaling pathway, and reducing the expressions of PHD, HIF-1α and VEGF proteins." (PMID 37446680, 2023). "Hence, identifying the interaction of the Nrf2/HO-1 pathway with the signaling pathways of HIF-1α and NF-ĸB plays an important role in controlling diabetic retinopathy and even discovering a drug." (PMID 34804425, 2021). "Furthermore, hypoxia-inducible factor 1 alpha (HIF1α) and VEGF are both implicated in the pathogenesis of diabetic retinopathy." (PMID 25268390, 2014). "However, HIF-1α may also exert adverse responses, such as the aggravation of diabetic retinopathy through the induction of VEGF." (PMID 33203103, 2020).
diabetic retinopathy (continued). "We explored differences in the DNA methylation statuses of PSMA6, PSMB5, HIF1A, and KEAP1 gene promoter regions in patients with type 1 diabetes and different diabetic retinopathy (DR) stages." (PMID 38927561, 2024). "HIF1α is a major factor in age-related macular degeneration (AMD), diabetic retinopathy, and retinoblastoma." (PMID 35144597, 2022). "A thorough understanding of the function of HIF-1α and its target genes may lead to identification of novel therapeutic targets for treating degenerative retinal diseases including glaucoma, age-related macular degeneration, diabetic retinopathy, and retinal vein occlusions." (PMID 28289375, 2017). "HIF-1α is particularly noteworthy as it directly upregulates VEGFA expression, linking hypoxia and angiogenesis pathways, which are central to the pathogenesis of diabetic retinopathy (DR)." (PMID 40002404, 2025). "The present study revealed that serum HIF-1α and survivin levels areincreased in patients with non-proliferative diabetic retinopathy comparedto those in patients without diabetic retinopathy." (PMID 38656026, 2024). "Aloe emodin is an anthraquinone derivative, which possesses the antiangiogenic effect on laser-induced choroidal neovascularization by inhibiting the HIF-1α/VEGF signaling pathway and has the potential to be developed for the prevention and treatment of diabetic retinopathy." (PMID 35860180, 2022). "Consecutively, HIF1-α activates the transcription of different target genes, including the Vascular Endothelial Growth Factor (VEGF), which is involved in angiogenesis and ocular neovascularization, a characteristic of diabetic retinopathy." (PMID 31130920, 2019). "Elevated HIF-1α and VEGF are generally accepted to be harmful for diabetic retinopathy, despite some studies found that anti-VEGF in DR rats had detrimental effects on neuronal cells (RGC, amacrine and bipolar cells) which are present in the inner layers of the retina." (PMID 28289375, 2017). "Furthermore, emodin can also impact diabetic retinopathy and cataract through inhibition of retinal neovascularization via modulation of HIF-1α/VEGF signaling pathway and through decreasing expressions of VEGFA, HIF-1α, and PHD-2." (PMID 34589130, 2021). "We observed elevated expressions of HIF-1α which plays a significant role in inducing transcription of the VEGF gene under hypoxic conditions and it is also responsible for induction of angiogenesis in pathological situations like diabetic retinopathy, tumor angiogenesis and coronary artery disease." (PMID 27835693, 2016). "In a retinal disease such as diabetic retinopathy, VIP may contribute to the protection of retinal neurons by reducing outer BRB dysfunction, probably through an inhibition of VEGF and of hypoxia-inducible factor 1α (HIF1-α), the main transcriptional regulator of VEGF expression." (PMID 31374938, 2019).
fibrosis (42 papers, 2013 to 2025). the formation of excess fibrous connective tissue in an organ or tissue in a reparative or reactive process. "Fibrosis is associated with sustained local tissue hypoxia, with HIF-1α directly implicated in TGF-β1-mediated fibrogenesis." (PMID 35871073, 2022). "In fibrosis, HIF-1α causes excessive ECM, vascular remodeling, and ineffective angiogenesis, all of which exacerbate chronic hypoxia and worsen pathofibrogenesis." (PMID 35457114, 2022). "Our data support the fact that a hypoxic microenvironment develops in the fibrotic lungs upon BLM in mice with the upregulation of hypoxic markers such as HIF-1α associated with an increase in [18F]FMISO lung uptake in correlation with fibrosis severity, as already demonstrated in oncology." (PMID 33580818, 2021). "In conclusion, our results provide new evidence that saffron ameliorates inflammatory infiltration in liver fiber processes, as well as vasculopathy and cellular hypoxia in a model of fibrosis through AKT/HIF-1α/VEGF signaling." (PMID 37959658, 2023). "Exo-HIF-1α significantly reduced left ventricular fibrosis area ratio and inner peripheral fibrosis length compared to the Exo group with upregulated pro-angiogenic factors." (PMID 35798726, 2022). "When analyzing IPF patient samples, HIF1α was expressed at lower levels in fibroblastic foci, and at higher levels in collagenous “old fibrosis” areas." (PMID 33805152, 2021). "After 8 weeks of the corresponding intervention, renal function, liver function, and protein expression of renal-fibrosis-related factors, HIF-1α, IL-1β, and c-Myc, were detected." (PMID 34211565, 2021). "We observed an increase in PKM expression in advanced fibrosis and cirrhosis, probably due to increased HIF-1α production." (PMID 28439208, 2016). "In addition, anoxic succinate has been shown to activate NLRP3 inflammasome through HIF-1α in an arthritic rat model, thereby exacerbating synovial fibrosis and inflammation." (PMID 39330487, 2024). "Both microRNA-98 and miR-345–5p ameliorate hepatic fibrosis through inhibiting HIF-1α signaling." (PMID 38074679, 2023). "The effects of NMN on hypoxia-associated adipose fibrosis, inflammation, NAD+/SIRT1 axis alteration, and HIF-1α activation were evaluated by real-time polymerase chain reaction (PCR), western blots, immunohistochemistry staining, immunoprecipitation, and assay kits." (PMID 36777361, 2023). "In our previous study, we also found that RES could reduce ROS production in activated platelets in a rat fibrosis model and inhibit HIF-1α expression in liver tissue in a rat ischemia-reperfusion model." (PMID 28817659, 2017). "The combination of low NOS2 expression to regulate relaxation and low HIF1A expression to regulate smooth muscle tone and contractility can potentially result in smooth muscle cramping and spasm, and subsequently to food getting stuck in the esophagus in a fibrosis-independent manner." (PMID 30455683, 2018). "The results from the present study provide evidence that hypoxia is a crucial factor in inducing the conversion of ECs into fibroblasts through an HIF-1α/VEGF dependent mechanism that consequently promotes skin microvascular remodeling and fibrosis in SSc." (PMID 35231032, 2022). "The results showed that liver sections from fibrosis patients had a lower level of VHL and higher levels of HIF-1α and HIF-2α compared with healthy sections, a finding which was confirmed in mice." (PMID 28112200, 2017). "It is noteworthy that despite increased intestinal fibrosis in HIF-1α KO mice, we did not detect massive expansion of the mesenchymal cell compartment." (PMID 38876796, 2024). "HIF-1α regulates VEGF under hypoxic conditions, controls angiogenesis, cell proliferation, and metastasis, and plays an important role in the occurrence and development of hepatic fibrosis and HCC." (PMID 38074679, 2023).
fibrosis (continued). "Some proteins of these genes have already been associated with pathophysiological processes in the kidney: in tubulointerstitial fibrosis (c-MYC, PTEN, STAT3, HIF-1α, PT53); podocyte injury (EGFR, PT53, CTNNB1, CREB1); epithelial-mesenchymal transition (PTEN); and glomerulosclerosis (DICER1, IL1β)." (PMID 37035314, 2023). "In agreement, bone marrow-derived mesenchymal stem cells (BM-MSCs) have been shown to inhibit the TGF-β/SMAD pathway to repress hypoxia-inducible factor 1 subunit alpha (HIF-1α) and VEGF protein expression in the ECM to restrict liver fibrosis and early HCC tumourigenesis." (PMID 33114183, 2020).